AKNAD1 (AKNA domain containing 1)
Synonyms: C1orf62; MGC26989
Tractability: No criterion of Open Targets' tractability assessment is met for any kind of drug.
Safety:
Unwanted effects reported when the protein is acted on. In parentheses: how it was acted on, where the effect was seen, and who reports it.
nausea and vomiting (source: ClinPGx)
Gene: Protein-coding gene on chromosome 1 (108,815,898 to 108,963,484, reverse strand). Ensembl gene ENSG00000162641.
Subcellular location (Human Protein Atlas): Cytosol; Cytokinetic bridge; Microtubules
Gene Ontology:
Cellular component: microtubule
Genetic constraint (gnomAD): Loss-of-function variants: 64 observed, 86.41 expected, observed/expected ratio (o/e) 0.74, 90% interval 0.61 to 0.91. The upper end of that interval is the gene's LOEUF score, 0.91, which puts it in group 3 of 6, group 1 being the genes least tolerant of losing a copy. Missense variants: 905 observed, 961.01 expected, observed/expected ratio (o/e) 0.94, 90% interval 0.89 to 1. Synonymous variants: 317 observed, 341.89 expected, observed/expected ratio (o/e) 0.93, 90% interval 0.85 to 1.02.
Homologues: Orthologues: chimpanzee AKNAD1 (98% identical), macaque AKNAD1 (91% identical), dog AKNAD1 (62% identical), mouse Aknad1 (43% identical), rat Aknad1 (42% identical), tropical clawed frog aknad1 (22% identical), zebrafish akna (14% identical). Paralogues in human: AKNA (17% identical).
Diseases named in the same sentence as AKNAD1 in open-access papers:
AKNAD1 is named in the same sentence as 2 diseases in open-access papers, as found by Europe PMC text mining. Sharing a sentence is not in itself a finding about the gene and the disease. The quoted sentences say what the papers report.
Type-2 Diabetes (2 papers, 2015 to 2020). "Only one research has identified a significant copy number variation in gene AKNAD1 which was validated to be associated with type-2 diabetes through stress of endoplasmic reticulum, suggesting a potential link of AKNAD1 and autoimmune diseases." (PMID 32727578, 2020).
AKNAD1 also shares sentences with these, for which no sentence is quoted: autoimmune disease (1 paper).